SEMA4D (semaphorin 4D)
Description:
Cell surface receptor for PLXNB1 and PLXNB2 that plays an important role in cell-cell signaling. Regulates GABAergic synapse development (By similarity). Promotes the development of inhibitory synapses in a PLXNB1-dependent manner (By similarity). Modulates the complexity and arborization of developing neurites in hippocampal neurons by activating PLXNB1 and interaction with PLXNB1 mediates activation of RHOA. Promotes the migration of cerebellar granule cells. Plays a role in the immune system; induces B-cells to aggregate and improves their viability (in vitro). Induces endothelial cell migration through the activation of PTK2B/PYK2, SRC, and the phosphatidylinositol 3-kinase-AKT pathway.
Synonyms: CD100; C9orf164; SEMAJ; coll-4; FLJ39737; A8; BB18; COLL4; GR3; M-sema-G
Tractability: Small molecule: it has a high-quality binding pocket. Antibody: a drug acting on it is in phase 2 or 3 trials; UniProt places it where antibodies can reach, with high confidence; its Gene Ontology location is reachable by antibodies, with high confidence; UniProt predicts a signal peptide or a membrane-spanning region. PROTAC: ubiquitination databases record sites on it; its protein half-life has been measured.
Gene: Protein-coding gene on chromosome 9 (89,360,787 to 89,498,167, reverse strand). Ensembl gene ENSG00000187764.
Subcellular location: Cell membrane; Secreted
Subcellular location (Human Protein Atlas): Plasma membrane; Basal body; Centrosome; Nucleoplasm; Primary cilium transition zone; Vesicles
Pathways (Reactome):
Developmental Biology: Other semaphorin interactions; Sema4D induced cell migration and growth-cone collapse; Sema4D mediated inhibition of cell attachment and migration
Gene Ontology:
Molecular function: protein binding; semaphorin receptor binding; signaling receptor activity; signaling receptor binding; transmembrane signaling receptor activity; chemorepellent activity; neuropilin binding; receptor ligand activity
Biological process: leukocyte aggregation; negative regulation of cell adhesion; negative regulation of transcription by RNA polymerase II; ossification involved in bone maturation; positive regulation of cell migration; positive regulation of collateral sprouting; positive regulation of GTPase activity; positive regulation of phosphatidylinositol 3-kinase/protein kinase B signal transduction; positive regulation of protein phosphorylation; regulation of cell projection organization; regulation of cell shape; regulation of dendrite morphogenesis; semaphorin-plexin signaling pathway; axon guidance; bone trabecula morphogenesis; cell adhesion; immune response; negative chemotaxis; negative regulation of apoptotic process; negative regulation of osteoblast differentiation; neural crest cell migration; positive regulation of inhibitory synapse assembly; positive regulation of Rho protein signal transduction; positive regulation of axonogenesis; positive regulation of intracellular signal transduction; and 1 more
Cellular component: extracellular region; plasma membrane; semaphorin receptor complex; GABA-ergic synapse; membrane; postsynaptic membrane
Genetic constraint (gnomAD): Loss-of-function variants: 20 observed, 63.96 expected, observed/expected ratio (o/e) 0.31, 90% interval 0.22 to 0.45. The upper end of that interval is the gene's LOEUF score, 0.45, which puts it in group 2 of 6, group 1 being the genes least tolerant of losing a copy. Missense variants: 900 observed, 1,111.8 expected, observed/expected ratio (o/e) 0.81, 90% interval 0.77 to 0.86. Synonymous variants: 432 observed, 468.09 expected, observed/expected ratio (o/e) 0.92, 90% interval 0.85 to 1.
Homologues: Orthologues: chimpanzee SEMA4D (99% identical), macaque SEMA4D (99% identical), rabbit SEMA4D (88% identical), mouse Sema4d (85% identical), pig SEMA4D (85% identical), rat Sema4d (85% identical), guinea pig SEMA4D (81% identical), dog SEMA4D (79% identical), tropical clawed frog sema4d (58% identical). Paralogues in human: SEMA4B (34% identical), SEMA4C (34% identical), SEMA4G (30% identical), SEMA4A (30% identical), SEMA3A (28% identical), SEMA4F (26% identical), SEMA3B (26% identical), SEMA3D (26% identical), SEMA3C (26% identical), SEMA3F (26% identical), SEMA3E (25% identical), SEMA3G (25% identical), and 7 more.
Diseases named in the same sentence as SEMA4D in open-access papers:
SEMA4D is named in the same sentence as 163 diseases in open-access papers, as found by Europe PMC text mining. Sharing a sentence is not in itself a finding about the gene and the disease. The quoted sentences say what the papers report.
breast carcinoma (27 papers, 2010 to 2025). "In breast carcinoma cells, when Sema4D binds to Plexin-B1 associated with ErbB2, it induces cell migration and metastasis." (PMID 39769452, 2024). "It has been shown that reduced Sema4D tissue expression in breast cancer patients was associated with a lower degree of disease-free survival and local disease recurrence." (PMID 30134791, 2018). "On the other hand, it was reported that the decreased expression of Sema4D and PlexinB1 was associated with local recurrence and poor prognosis in breast cancer." (PMID 27456345, 2016). "We propose a model of lytic skeletal metastasis where breast cancer cells newly colonizing a site in bone produce Sema4D which inhibits osteoblasts and causes them to produce IL-8, promoting osteoclast function." (PMID 26910109, 2016). "In breast carcinoma cells, the Sema4D activation of Plexin B1 leads to its tyrosine phosphorylation by MET, creating a docking site for the SH2 domain of Grb2." (PMID 39769452, 2024). "SEMA4D is most extensively studied in oncology and it is currently considered a promising target for antitumor therapy for breast cancer." (PMID 37893159, 2023). "MCF7, a breast cancer cell line which expresses high levels of PlexinB1, were treated with Sema4D, and RanGTP levels were detected with RanBP1(RBD)-GST, which binds to GTP-bound Ran specifically." (PMID 37563360, 2023). "SEMA4D has been confirmed to be expressed at high levels in a variety of tumors, including prostate cancer, colon cancer, breast cancer, oral cancer, lung cancer, pancreatic cancer, head and neck carcinoma, and soft tissue sarcoma." (PMID 37287907, 2023). "In keeping with these data, Sema4D knock-down in breast cancer cells was found to suppress tumor growth in vivo, angiogenesis, and bone metastases formation in mouse models." (PMID 33537086, 2021). "The relevance of Sema4D in the tumor microenvironment was confirmed in multiple tumor types beyond breast carcinoma, which has prompted the preclinical validation of targeted antibodies interfering with its function." (PMID 33537086, 2021). "This same pathway was studied in more mechanistic detail in breast carcinoma cells, where SEMA4D signaling via its receptor Plexin-B1 either activated or suppressed cell migration." (PMID 31877778, 2019). "For Caucasian breast cancer patients, SEMA4D's high affinity receptor Plexin-B1 showed a significant positive correlation with survival." (PMID 30762724, 2019). "In epithelial cells, SEMA4D triggered invasive growth and stimulated migration in breast cancer cells in concert with ErbB-2 signaling." (PMID 31877778, 2019). "Jiang and coworkers confirmed high Sema4D protein in breast cancer cell lines compared to normal breast epithelial cells." (PMID 29971044, 2018). "This notion is supported by a decrease in skeletal metastasis when Sema4D was knocked down using shRNA in the MDA-MB-231 breast cancer model." (PMID 29971044, 2018). "Silencing Sema4D expression via RNA interference decreased the number of osteolytic metastases in a breast cancer murine model." (PMID 29748532, 2018). "In an array of 888 genes, Sema4D mRNA was highest in early stage breast cancer compared to normal tissue and downregulated in advanced disease." (PMID 29971044, 2018). "We observed that silencing of Sema4D expression in breast cancer cells through shRNA resulted in smaller and fewer skeletal metastases over time and greater life expectancy in a mouse model compared to controls." (PMID 26910109, 2016). "Semaphorin 4D (Sema4D) was also reported to be responsible for TAM mediated angiogenesis in a murine breast cancer model." (PMID 27886105, 2016). "Taken together, these results suggest that Sema4D from breast cancers can inhibit mineralization by osteoblasts and induce their production of the osteoclast stimulating factor IL-8 in a RhoA-dependent manner." (PMID 26910109, 2016).
breast carcinoma (continued). "For example, Sema4D is produced by osteoclasts, and we have demonstrated its expression in primary breast cancers in a tumor tissue array, but lymphocytes present in the metastatic microenvironment would produce Sema4D as well." (PMID 26910109, 2016). "To determine if Sema4D from breast cancer cell lines can affect osteoblast-mediated mineralization, we needed to alter production of this protein." (PMID 26910109, 2016). "This study demonstrated that the antimigratory or promigratory effects of Sema4D in breast cancer cell lines depend on the stoichiometry of the expression of Plexin-B1, Met and ErbB-2." (PMID 20858260, 2010). "However, the interaction of SEMA4D in disseminating breast cancer cells with PLXNB1 of brain endothelial cells can contribute to the brain-tropic metastasis of cancer." (PMID 40818975, 2025). "Furthermore, in vivo studies on other types of cancer, such as acute myeloid leukemia, bladder cancer, and breast cancer have shown that the inhibition of SEMA4D has therapeutic potential." (PMID 39329961, 2024). "The role of Sema4D in breast cancer appears quite complex based on current literature." (PMID 33537086, 2021). "SEMA4D could be a prospective biomarker for prognostic prediction of various malignancies except breast cancer." (PMID 30762724, 2019). "In summary, the present analysis demonstrated that SEMA4D could be a prospective biomarker for prognostic prediction of various malignancies except breast cancer." (PMID 30762724, 2019). "Furthermore, antibody-mediated Sema4D blockade showed a promising immunomodulatory effect in murine colorectal and breast cancer models." (PMID 29748532, 2018). "Moreover, anti-Sema4D Ab delayed tumor growth and prolonged survival by 29% in a murine colon cancer model and Sema4D silencing by RNA interference reduced the breast cancer related bone metastasis." (PMID 30134791, 2018). "In addition, knockdown of Sema4D by shRNA inhibit breast cancer proliferation and tumor growth in xenografts." (PMID 29971044, 2018). "We would like to thank Meenakshi A. Chellaiah of the University of Maryland Dental School for the luciferase-expressing breast cancer cell lines and Ernest Smith and Maurice Zauderer of Vaccinex, Inc., for providing the anti-SEMA4D antibody and offering technical support." (PMID 26910109, 2016). "We have previously shown that breast cancers overexpress Sema4D." (PMID 26910109, 2016). "Breast cancers and other epithelial malignancies overexpress Sema4D, so we theorized that tumor cells could be exploiting this pathway to establish lytic skeletal metastases." (PMID 26910109, 2016). "Another study employing breast cancer cell lines in Sema4D knockout mice demonstrated that the presence of Sema4D in the tumor microenvironment is important for tumor growth and metastasis, which is attributed to tumor vessel maturation induced by Sema4D." (PMID 20858260, 2010). "The findings presented here demonstrate that Sema4D enhances skeletal metastasis and could represent a new therapeutic target in the suppression of skeletal metastases for a subset of bone homing malignancies such as breast cancer." (PMID 26910109, 2016). "Myeloma cells, as well as breast cancers, express MMP14 (MT1-MMP), which releases membrane-bound Sema4D by proteolytic cleavage." (PMID 29971044, 2018). "We did not specifically measure breast cancer cell proliferation, invasion or vascularity in our experiments in an attempt to avoid duplication of already published reports, but Sema4D (or loss thereof) could certainly influence progression of metastatic lesions through these mechanisms." (PMID 26910109, 2016). "Sema4D, also known as CD100, is a transmembrane molecule of 150 kDa of semaphorins IV subfamily, and upregulated in multiple tumor tissues, such as lung, colon, and breast cancer." (PMID 35155237, 2022).
breast carcinoma (continued). "MDA-MB-231 cells, a human breast cancer cell line that forms osteolytic bone metastases when inoculated into the arterial circulation of mice, expresses high levels of Sema4D relative to MCF-12A or T47D cells, lines which do not spread to bone." (PMID 26910109, 2016). "Although SEMA4D has been previously explored in many types of cancer, including HNSCC, prostate cancer, colon cancer, breast cancer and lung cancer, its function remains unknown in ovarian cancer." (PMID 23202951, 2012).
ovarian carcinoma (15 papers, 2012 to 2025). A malignant neoplasm originating from the surface ovarian epithelium. "The coexpression of MET and plexin-B1, the receptor of Sema4D, was associated with advanced-stage breast and ovarian carcinoma as indicated in MET/plexin-B1 double-positive tumors." (PMID 39742369, 2024). "Immunofluorescent staining of tumor tissues, obtained from 124 ovarian cancer patients, demonstrated the association of SEMA4D/plexin-B1 high expression with increased amounts of CD31+ cells." (PMID 34209679, 2021). "Furthermore, elevated expression of Sema4D in macrophages was associated with poor prognosis in ovarian cancer and facilitated the differentiation of macrophages toward the M2-like lineage." (PMID 39425000, 2025). "Our previous study demonstrated that miR-214 can directly target Sema4D and inhibited cell proliferation in human ovarian cancer cell line SKOV-3." (PMID 37986114, 2023). "Together with VEGF, Sema4D is thereby considered an independent adverse prognostic factor for epithelial ovarian cancer patients." (PMID 33537086, 2021). "The expressions of VEGF and SEMA4D, two crucial proteins promoting tumor angiogenesis, were detected in ovarian cancer tissues by immunohistochemistry." (PMID 31105696, 2019). "VEGF and SEMA4D had a positive correlation with the malignant degree of ovarian cancer, and SEMA4D can serve as an independent prognostic factor." (PMID 29308068, 2018). "Here, we try to further understand the mechanism by which SEMA4D promotes angiogenesis in ovarian cancer." (PMID 29308068, 2018). "VEGF and SEMA4D have synergistic effects on the promotion of angiogenesis in epithelial ovarian cancer." (PMID 29308068, 2018). "Here, we mainly explore the role of SEMA4D in the process of angiogenesis in epithelial ovarian cancer." (PMID 29308068, 2018). "Our previous study demonstrated that miR-214 could directly target Sema4D in human ovarian cancer cells." (PMID 37986114, 2023). "By screening the 5′ non-coding region before the ATG start codon of Sema4D in endothelial and cancer cells including colorectal, nasopharyngeal and ovarian carcinoma, and leukemic cells, a recent paper identified four possible HRE, with different functions depending on the cell type." (PMID 33858502, 2021). "Our results also showed the correlation of SEMA4D and VEGF positive expressions were closely in EOC tissues, which hinted targeting SEMA4D might serve as a parallel option for traditional antiangiogenic therapy with single regimen in ovarian cancer." (PMID 31105696, 2019). "VEGF and SEMA4D were positively correlated with the malignant degree of ovarian cancer." (PMID 29308068, 2018). "Over-expressions of SEMA4D and VEGF were closely related to EOC tissues with LN metastasis and patients' response to BC, which showed a poor prognosis for ovarian cancer patients." (PMID 31105696, 2019). "Only one myeloma cell line produced high Sema4D (MR20: 104.45 ng/ml) compared to all others (mean ± SD: 1.6 ± 1.4 ng/ml), while there were undetectable Sema4D levels in the supernatants of all ovarian cancer cell lines." (PMID 29748532, 2018). "Univariate analysis indicated that the overall survival and progression-free survival of epithelial ovarian cancer patients with high expression of Sema4D were lower than in patients with Sema4D-negative tumors." (PMID 33537086, 2021). "Positive expression of SEMA4D in epithelial ovarian cancer was associated with poor OS and decreased progression-free survival (PFS) in comparison with samples of negative SEMA4D expression." (PMID 34209679, 2021). "PD-L1, SEMA4D, and VEGF expressions in ovarian cancer tissues." (PMID 31105696, 2019). "Interestingly, it was observed that VEGFR-2, plexin-B1, and Sema4D control the expression of CD31, MMP-2, and VE-cadherin in ovarian cancer cells, which are the markers and initiators of angiogenesis and VM." (PMID 31612116, 2019).
ovarian carcinoma (continued). "Nevertheless, the function and expression of SEMA4D in epithelial ovarian cancer (EOC) is as yet not well understood." (PMID 23202951, 2012).
head and neck squamous cell carcinoma (12 papers, 2010 to 2024). A squamous cell carcinoma that arises from any of the following anatomic sites: lip and oral cavity, nasal cavity, paranasal sinuses, pharynx, larynx, and salivary glands. "Knockdown of semaphorin 4d (Sema4D) in a human head and neck squamous cell carcinoma (HNSCC) cell line resulted in a loss of MDSC function, as shown by a decrease in the production of the immunosuppressive cytokines arginase-1, TGF-β, and IL-10 by MDSCs." (PMID 37039643, 2023). "Soluble Sema4D levels in plasma may be regarded as a biomarker in head and neck squamous cell carcinoma, and high levels of soluble Sema4D are associated with the INF-γ-negative tumor microenvironment." (PMID 35401878, 2022). "For instance, PLXNB1/SEMA4D promotes metastasis of head and neck squamous cell carcinoma by inducing epithelial–mesenchymal transition." (PMID 39443302, 2024). "Plexin-B1 transduces signals of sema4D (also known as CD100) in head and neck squamous cell carcinoma (HNSCC) in a xenograft mouse model." (PMID 37627074, 2023). "As soluble Sema4D plays an important role in interacting with the tumor microenvironment, its levels in plasma are regarded as a biomarker of poor prognosis in head and neck squamous cell carcinoma." (PMID 35401878, 2022). "Sema4D is highly expressed in cell lines derived from head and neck squamous cell carcinomas (HNSCCs)." (PMID 23050142, 2012). "In one study employing head and neck squamous cell carcinoma cell lines with high expression of Sema4D, tumor growth and tumor angiogenesis in vivo were greatly impaired in the absence of Sema4D." (PMID 20858260, 2010). "The Gutkind laboratory demonstrated that SEMA4D, cleaved from head and neck squamous cell carcinoma cells (HNSCC), enhances endothelial cell migration by binding to Plexin B1 receptors expressed on these cells." (PMID 37504226, 2023). "When looking specifically at the expression of Sema4D in tumor samples, this was found to be elevated in several tumor types like HNSCC (head and neck squamous cell carcinoma), prostate, colon, breast and lung cancer." (PMID 25815459, 2015). "Additional phase Ib/II studies of anti-SEMA4D in combination with anti-PD-L1 and/or anti-CTLA-4 for treatment of melanoma and head and neck squamous cell carcinoma (HNSCC) are anticipated." (PMID 28649381, 2017).